KRT8P15 (keratin 8 pseudogene 15)
Gene: Processed pseudogene on chromosome 2 (202,840,331 to 202,841,781, reverse strand). Ensembl gene ENSG00000233579.
Diseases named in the same sentence as KRT8P15 in open-access papers:
KRT8P15 is named in the same sentence as 1 disease in open-access papers, as found by Europe PMC text mining. Sharing a sentence is not in itself a finding about the gene and the disease. The quoted sentences say what the papers report.
myocardial infarction (1 paper, 2023). Gross necrosis of the myocardium, as a result of interruption of the blood supply to the area, as in coronary thrombosis. "The gene KRT8P15 was additionally selected as it appeared in Myocardial infarction and CAD." (PMID 37491351, 2023).